CD1A (CD1a molecule)
Description:
Antigen-presenting protein that binds self and non-self lipid and glycolipid antigens and presents them to T-cell receptors on natural killer T-cells.
Synonyms: CD1; FCB6; HTA1; R4; T6
Tractability: Small molecule: a structure with a bound ligand is known; it has a high-quality binding pocket. Antibody: UniProt places it where antibodies can reach, with high confidence; its Gene Ontology location is reachable by antibodies, with high confidence; UniProt predicts a signal peptide or a membrane-spanning region. PROTAC: ubiquitination databases record sites on it.
Gene: Protein-coding gene on chromosome 1 (158,254,424 to 158,258,269, forward strand). Ensembl gene ENSG00000158477.
Subcellular location: Cell membrane; Membrane raft; Endosome membrane
Pathways (Reactome):
Immune System: Immunoregulatory interactions between a Lymphoid and a non-Lymphoid cell
Gene Ontology:
Molecular function: protein binding; endogenous lipid antigen binding; exogenous lipid antigen binding; lipopeptide binding
Biological process: antigen processing and presentation, endogenous lipid antigen via MHC class Ib; antigen processing and presentation, exogenous lipid antigen via MHC class Ib; immune response; positive regulation of T cell mediated cytotoxicity
Cellular component: endosome membrane; membrane raft; plasma membrane; external side of plasma membrane
Genetic constraint (gnomAD): Loss-of-function variants: 51 observed, 39.15 expected, observed/expected ratio (o/e) 1.3, 90% interval 1.04 to 1.64. The upper end of that interval is the gene's LOEUF score, 1.64, which puts it in group 6 of 6, group 1 being the genes least tolerant of losing a copy. Missense variants: 455 observed, 424.17 expected, observed/expected ratio (o/e) 1.07, 90% interval 0.99 to 1.16. Synonymous variants: 160 observed, 158.74 expected, observed/expected ratio (o/e) 1.01, 90% interval 0.88 to 1.15.
Homologues: Orthologues: chimpanzee CD1A (97% identical), macaque CD1A (87% identical), rabbit CD1C (63% identical), dog CD1A8 (54% identical), zebrafish mhc1lla (18% identical), zebrafish si:dkey-52p2.5 (18% identical), zebrafish mhc1laa (18% identical), zebrafish mhc1lfa (17% identical), zebrafish mhc1lja (17% identical), zebrafish mhc1lba (17% identical), zebrafish mhc1lda (17% identical), zebrafish mhc1lga (16% identical), and 1 more. Paralogues in human: CD1B (59% identical), CD1C (58% identical), CD1E (55% identical), CD1D (51% identical), HLA-A (26% identical), HLA-F (26% identical), HLA-E (25% identical), HLA-G (25% identical), HLA-B (24% identical), HLA-C (24% identical), MR1 (23% identical), HFE (21% identical), and 10 more.
Diseases named in the same sentence as CD1A in open-access papers:
CD1A is named in the same sentence as 228 diseases in open-access papers, as found by Europe PMC text mining. Sharing a sentence is not in itself a finding about the gene and the disease. The quoted sentences say what the papers report.
Langerhans cell histiocytosis (118 papers, 2006 to 2026). Langerhans cell histiocytosis (LCH) is a systemic disease associated with the proliferation and accumulation (usually in granulomas) of Langerhans cells in various tissues. "Conversely, ulcerations associated with Langerhans cell histiocytosis are marked by the presence of atypical large cells of Langerhans cell origin, which are immunohistochemically positive for CD1a and exhibit ultrastructural Birbeck granules." (PMID 39857083, 2025). "Langerhans cell histiocytosis (LCH) is an inflammatory neoplasia resulting from clonal expansions of CD207 + CD1a + cells, which causes tissue destruction and a wide range of organ involvement." (PMID 38231288, 2024). "Langerhans cell histiocytosis (LCH) is a rare disease caused by the clonal expansion of CD1a+/CD207+ LCH cells." (PMID 36246871, 2022). "Langerhans cell histiocytosis (LCH) is a disease caused by clonal expansion of CD1a+/CD207+ cells and is characterized by organ involvement and dysfunction." (PMID 39935470, 2025). "Skin biopsy confirmed Langerhans cell histiocytosis (LCH), with immunohistochemistry demonstrating diagnostic markers CD1a(+), Langerin(+), and S-100(+)." (PMID 41462262, 2025). "Langerhans cell histiocytosis (LCH) is a rare systemic hematologic disorder caused by clonal expansion of myeloid precursors that differentiate into CD1a+/CD207+ dendritic cells in lesions that leads to a spectrum of organ involvement and dysfunction." (PMID 40416903, 2025). "Langerhans cell histiocytosis (LCH), a granulomatous tumorous lesion consisting of CD1a‐positive clonal immature dendritic cells in association with various inflammatory cells, develops in tissues including bone, skin, lungs, and lymph nodes." (PMID 36051086, 2022). "The presence of histiocytes that are S100+, CD68+, and CD1a help distinguish RDD from common lookalikes such as Langerhans cell histiocytosis." (PMID 41552389, 2026). "Erdheim-Chester disease (ECD) is an ultra-rare non-Langerhans cell histiocytosis characterized by CD68-positive, CD1a/S100-negative histiocytes, frequently associated with BRAF V600E and MAPK pathway mutations." (PMID 41497010, 2025). "Langerhans cell histiocytosis (LCH) is a clonal myeloid neoplasm of CD1a-positive dendritic cells, with an estimated pediatric incidence of ~ 5 per million children and a peak occurrence between 1 and 4 years of age." (PMID 41458274, 2025). "Langerhans cell histiocytosis is a rare inflammatory neoplasm of myeloid origin characterized by the presence of classic CD1A+CD207+ histiocytes notorious for aberrant function secondary to activating somatic mutations in the MAPK (RAS–RAF–MEK–ERK) pathway." (PMID 40287907, 2025). "Langerhans’ cell histiocytosis can be differentiated from RDD by testing immunoreactivity to S-100 and CD1a; while Langerhans’ cell histiocytosis is reactive to both S-100 and CD41a, RDD is only reactive to S-100." (PMID 41487792, 2025). "Based on the characteristic clinical presentation, histopathological findings (H&E), and confirmatory IHC profile (S-100+, CD1a+, Langerin+), a diagnosis of Langerhans cell histiocytosis (LCH) was established." (PMID 41462262, 2025). "Langerhans cell histiocytosis (LCH) is the monoclonal proliferation of Langerhans cells presenting with CD1a + /CD207 (Langerin) + markers in lesions." (PMID 38245681, 2024). "Langerhans cell histiocytosis (LCH) is a rare haematological neoplasm characterized by the accumulation of CD1a+, CD207/Langerin+ histiocytes within inflammatory lesions." (PMID 35915468, 2022). "Langerhans cell histiocytosis is a disease characterized by aggregation of CD1a+/CD207+ cells and inflammatory cell infiltration." (PMID 36177069, 2022). "Langerhans cell histiocytosis (LCH) is an orphan disease characterized by clonal proliferation of abnormal CD1a+/CD207+ myeloid precursors cells." (PMID 35207181, 2022).
Langerhans cell histiocytosis (continued). "LCH is a rare disease characterized by heterogeneous lesions, e.g., granulomatous lesions and histiocytosis X lesions, and the pathological features of affected tissues usually manifests as positive staining of CD1a and langerin." (PMID 36160158, 2022). "Langerhans cell histiocytosis (LCH) is a rare disease characterized by clonal expansion of CD1a+/CD207+ cells in lesions." (PMID 35547871, 2022). "Langerhans cell histiocytosis (LCH) is a CD1a and/or S100 antigen-positive inflammatory disease consisting of characteristic Langerhans cells." (PMID 34274753, 2021). "Langerhans cell histiocytosis lesions are characterized by CD1a+ myeloid lineage LCH cells and an inflammatory infiltrate of cytokines and immune cells, including T cells." (PMID 34956202, 2021). "The differential diagnosis include benign lymphoid hyperplasia with sinus histiocytosis which will lack the emperipolesis seen in RDD, Langerhans cell histiocytosis in which the cells are positive for S100, langerin, and CD1a." (PMID 32085787, 2020). "Langerhans cell histiocytosis is characterized by accumulation of clonal CD1a-positive immature dendritic cells, so-called Langerhans cell histiocytosis cells, together with eosinophils, macrophages, lymphocytes and osteoclast-like giant cells." (PMID 32468287, 2020). "Histopathological and immunohistochemical studies revealed granulomatousmaterial with monoclonal Langerhans cells, Birbeck granules, and CD1a positivity,confirming the diagnosis of Langerhans cell histiocytosis (LCH)." (PMID 30369670, 2018). "Langerhans cell histiocytosis (LCH) is a rare disease caused by the proliferation of abnormal bone marrow-derived, CD1a-positive Langerhans cells, which infiltrate various organs." (PMID 30187131, 2018). "Langerhans cell histiocytosis (LCH) features inflammatory granuloma characterised by the presence of CD1a+ dendritic cells or ‘LCH cells’." (PMID 22506009, 2012). "The presence of increased numbers of Langerhans' cells in BAL fluid (identified by staining with antibodies against CD1a) with a proportion greater than 5 percent is also strongly suggestive of pulmonary Langerhans'-cell histiocytosis." (PMID 20727133, 2010). "Among other situations, the diagnosis of Langerhans cell histiocytosis can be performed with the use of the monoclonal antibodies revealing the presence of CD1a positive cells (in more than 5% of the BAL cells)." (PMID 20727133, 2010). "Langerhans cell histiocytosis affects mainly young children and features an accumulation of CD1a+ dendritic Langerhans cells in the bone, skin, and other organs." (PMID 17034629, 2006). "CD1a positivity in presumed RDD can signal overlap with Langerhans cell histiocytosis." (PMID 41351624, 2025). "However, immunohistochemical (IHC) staining demonstrated a dense dermal infiltration of leukocytes and eosinophils along with CD1a‐positive histiocytes, suggesting a possible diagnosis of Langerhans cell histiocytosis (LCH)." (PMID 41319099, 2025). "Langerhans cell histiocytosis is characteristically positive for langerin, CD1a, and S100 and may show variable or dot-like positivity for CD68." (PMID 40398847, 2025). "In langerhans cell histiocytosis, CD1a, CD207 (langerin), S100, CD68, and HLA-DR were positive." (PMID 39850815, 2024). "Similarly, S100 and CD1a are consistently positive for Langerhans cell histiocytosis thus making them reliable in distinguishing xanthomas from Langerhans disease." (PMID 38502367, 2024). "Langerhans cell histiocytosis (LCH) is a disease originating from abnormal proliferation of CD1a+/CD207+ myeloid dendritic cells and characterized by activation of the mitogen-activated protein kinase (MAPK)/extracellular signal-regulated kinase (ERK) signaling pathway." (PMID 37551332, 2021).
Langerhans cell histiocytosis (continued). "In this report, a case of a 44-year-old female, who was intermittently followed due to a suspected persistent cutaneous candidiasis in which a skin biopsy revealed Langerhans cell histiocytosis with immunohistochemistry positive for CD1a and S100 protein, is described." (PMID 34956779, 2021). "The CD1a+ DCH may have the typical aspect of Langerhans cell histiocytosis (LCH), i.e., round, medium-sized histiocytes with eosinophilic cytoplasm and, in some cases, large reniform or “coffee bean” shaped nuclei." (PMID 34449607, 2021). "Langerhans cell histiocytosis (LCH) is a rare inflammatory myeloid neoplasm characterized by organ infiltration by pathological myeloid dendritic cells that share surface markers with epidermal Langerhans cells (CD1a+/CD207+)." (PMID 32967635, 2020). "However, it is important to note that CD1a reactivity is more typical of Langerhans cell histiocytosis (LCH) while S-100 reactivity is more characteristic of RDD." (PMID 23497062, 2013). "However, the circumscribed rather than infiltrative pattern of this solitary intrapituitary nodule, one devoid of CD1a immunoreactivity, was an intuitive obstacle against seriously considering Langerhans cell histiocytosis." (PMID 21970745, 2011). "Langerhans cell histiocytosis (LCH) is an uncommon paediatric disorder characterised by the clonal accumulation of CD1a-positive, langerin-positive dendritic cells in various tissues." (PMID 41552070, 2025). "Langerhans cell histiocytosis (LCH) is a rare myeloid neoplastic disorder characterized by the abnormal proliferation and accumulation of dendritic cells bearing the CD1a+/CD207+ phenotype." (PMID 40443606, 2025). "Langerhans cell histiocytosis (LCH) is a rare disease characterized by CD1a/CD207-positive dendritic cells." (PMID 40979825, 2025). "Langerhans cell histiocytosis (LCH) is a clonal, neoplastic proliferative disease characterized by the proliferation of immature dendritic cells (CD1a+/CD207+), leading to tissue and organ infiltration and subsequent functional impairments." (PMID 39346019, 2025). "Langerhans cell histiocytosis (LCH) is a rare neoplasm characterized by the clonal proliferation of myeloid dendritic cells which express CD1a and CD207 (langerin)." (PMID 39873807, 2025). "Langerhans cell histiocytosis (LCH) is a rare systemic disease that is characterized by the accumulation of CD1a/Langerin-positive cells in various tissues and organs." (PMID 36826750, 2023). "Langerhans cell histiocytosis (LCH) is a neoplastic transformation of myeloid precursors characterized by the expression of CD1a, CD68, CD207 (Langerin), and S-100." (PMID 37522932, 2023). "Langerhans cell histiocytosis (LCH) is a rare, clonal disorder derived from CD1a-positive and CD207-positive immature myeloid dendritic cells, with a wide range of clinical presentations." (PMID 35841042, 2022). "Langerhans cell histiocytosis (LCH) is a rare neoplastic disorder characterized by the clonal proliferation of CD1a +/CD 207 + dendritic cells, whose features are similar to those of epidermal Langerhans cells." (PMID 35204491, 2022). "Langerhans cell histiocytosis (LCH) is a rare disease characterized by the accumulation of CD1a-positive (CD1a+)/CD207+ histiocytes with inflammatory lesions in various organ systems." (PMID 35379272, 2022). "Langerhans cell histiocytosis (LCH) is a disease driven by misguided myeloid differentiation, with the feature of accumulated CD1a+/Langerin+ Langerhans cells in lesions." (PMID 36246871, 2022). "Langerhans cell histiocytosis (LCH) is a rare condition characterized by the accumulation of CD1a or Langerin-positive dendritic cells in various organs, often leading to organ dysfunction." (PMID 34980070, 2022). "The cells were strongly positive for CD1a (200×) and S100 protein, characteristic for Langerhans cell histiocytosis (LCH)." (PMID 35845219, 2021).
Langerhans cell histiocytosis (continued). "Langerhans cell histiocytosis (LCH) is a rare systemic disorder characterized by an infiltration of CD1a+/langerin+ histiocytes, commonly involving bone, skin, and lymph nodes in children." (PMID 32676232, 2020). "Immunohistochemistry showed immunoreactivity for S100, CD1a, and langerin, suggesting, along with the anatomopathological exam and clinical history, Langerhans cell histiocytosis (LCH)." (PMID 31777366, 2019). "Langerhans cell histiocytosis (LCH) is an uncommon disorder in which S-100- and CD1a-positive cells infiltrate one or more organs, primarily the skeletal system, skin, thyroid gland, liver, lung, spleen and/or hematopoietic system." (PMID 31254905, 2019). "Langerhans cell histiocytosis (LCH) lesions are defined by the presence of CD1a+/CD207+ myeloid cells, but many other immune cells are present including unconventional T cells, which have powerful immunoregulatory functions." (PMID 30405183, 2018). "Langerhans cell histiocytosis (LCH) is a generic term that identifies several clinical cases characterized by the proliferation of distinctive cells that are S100 and CD1a positive and contain Birbeck granules in their cytoplasm." (PMID 28977321, 2017). "Langerhans cell histiocytosis (LCH) is characterized by lesions that include CD1a+CD207+ dendritic cells, along with inflammatory cell infiltrates." (PMID 27833773, 2016). "While Langerhans' cell histiocytosis exhibits the proliferation of CD1a(+), Langerin(+), S100(+) Langerhans' dendritic cells, ECD is hypothesized to originate from the proliferation and migration of CD68(+), CD1a(−) non Langerhans' histiocytes of monocyte-macrophage descent." (PMID 24011030, 2013). "Langerhans cell histiocytosis (LCH) is the proliferation and accumulation of CD1a+ dendritic cells, known as Langerhans cells, and it typically manifests in one or more organ systems such as the skin, lung, bone, bone marrow, and liver." (PMID 40606814, 2025). "Langerhans cell histiocytosis (LCH), the most common histiocytic disorder in children, features lesions of aberrant CD1a/CD207 (langerin)–expressing Langerhans cells with immune infiltrates." (PMID 41176307, 2025). "Thoracoscopic lung biopsy with immunohistochemistry (CD1a+, CD45+, S100+) confirmed Langerhans cell histiocytosis." (PMID 41458274, 2025). "Erdheim-Chester disease is a multisystem non-Langerhans cell histiocytosis with fibrosis characterized by CD68+, CD1a-, and S100- expression." (PMID 40351997, 2025). "Langerhans cell histiocytosis (LCH) is a rare disorder of unknown etiology, characterized by clonal proliferation of CD1a- and/or CD207-positive dendritic cells." (PMID 40979825, 2025). "The Langerhans cells were reactive to CD1a and BRAF; hence, a diagnosis of carcinosarcoma ex pleomorphic adenoma with Langerhans cell histiocytosis was given." (PMID 37621779, 2023). "Langerhans cell histiocytosis (LCH) is a rare inflammatory and myeloproliferative neoplasm characterized by the proliferation and accumulation of histiocytes that express CD1a, Langerin (CD207+), and S-100 proteins." (PMID 37237668, 2023). "The cells were positive for Langerin, CD1a, S100, and CD68 immunostains, consistent with cutaneous Langerhans cell histiocytosis." (PMID 36619508, 2022). "Langerhans cell histiocytosis (LCH) is considered a neoplasia of Langerhans cells or a histiocytic tumor expressing S-100, CD1a and CD207." (PMID 28445138, 2017). "Langerhans cell histiocytosis was confirmed by neuroendoscopic procedures, and immunohistochemical staining showed that all cases (7/7) were positive for CD68, CD1a, Langerin, and S-100." (PMID 27760550, 2016). "Erdheim–Chester disease (ECD) is a rare, multiorgan, non-Langerhans cell histiocytosis of uncertain origin, characterized by systemic xanthogranulomatous infiltration from CD68+CD1a- histiocytes." (PMID 26512552, 2015).